KRAS (KRas proto-oncogene, GTPase)
Diseases named in the same sentence as KRAS in open-access papers (continued):
Sharing a sentence is not in itself a finding about the gene and the disease.
colon carcinoma (continued). "Activation of the RAS pathway has been described as a mechanism of primary or secondary resistance in colon cancer, where the presence of KRAS activating mutations in the primary tumor is a negative predictive factor of response to the anti-EGFR monoclonal antibodies cetuximab and panitumumab." (PMID 25691052, 2015). "Among GNAS mutant colon cancers, we identified mutations in the KRAS and BRAF oncogenes in nine of the ten (90%) cases, a fraction that is significantly higher than the overall frequency of KRAS and BRAF mutations in the tumor cohort (P<0.0305, Fisher's exact test)." (PMID 24498230, 2014). "In colon cancer, the negative predictive value of KRAS mutation status for the anti-EGFR antibodies efficacy has been reported first in retrospective studies then definitively confirmed by retrospective analysis of tumors of patients included in large prospective trials." (PMID 24212636, 2011). "As both BRAF and KRAS mutations have been observed in the earliest identified colonic neoplasms, and recent papers have provided evidence that induction of the ras oncogenic pathway will result in DNA hypermethylation, a causative effect of BRAF/KRAS mutations is likely." (PMID 20444249, 2010). "Also, recently a study of colon cancer patients showed that PIK3CA mutations did not confer any significant effect on mortality among patients with KRAS-mutated tumors and is consistent with our findings on tumors growth in HCT116 cells." (PMID 19492075, 2009). "In terms of the carcinogenic mechanism, colon tumors often displayed increased expression levels of HOX gene family 30, higher pathway activities of MAPK cascades 31, and constitutive activation of KRAS 32 and BRAF 33, 34, as compared to rectal tumors." (PMID 41323778, 2025). "Subsequently, we performed single-molecule imaging of oncogenic KRAS mutants between 2 and 5 min after EGF stimulation in SW48 colon cancer cells that had undergone 1 h of serum starvation." (PMID 40949096, 2025). "Moreover, inhibiting USP25 could temper KRAS signaling in pancreatic, lung, and colon cancer cells carrying various activating mutations in KRAS and for one of the mutants, KRASQ61H, no direct inhibitors are available." (PMID 40473213, 2025). "Next, we performed single-molecule imaging of tdStayGold-KRAS WT, which was sparsely expressed in SW48 colon cancer cells." (PMID 40949096, 2025). "This approach has shown efficacy in colon cancer and NSCLC patients with mutant KRAS G12D and HLA-C*08:02 expression." (PMID 38668053, 2024). "As demonstrated in this study, this complex efficiently suppressed three human colon cancer cells: double wild type; BRAF mutant; and KRAS mutant." (PMID 37099199, 2023). "CDX2 status, tumour location, tumour size, TILs, KRAS and BRAF status were ranked of lowest importance in determining prognosis in colon cancer." (PMID 35323316, 2022). "After screening for oncogenes or suppressor genes, KIT, KRAS, BRAF, and JAK2 were significantly higher in colon cancer ECs." (PMID 35755820, 2022).
colon carcinoma (continued). "In colon cancer, DCLK1 and the MET are upregulated in KRAS G12 mutant expressing KRAS cells, whereas ZO-2 is upregulated in KRAS G13D." (PMID 35785187, 2022). "Oncogenic KRAS is involved in mitochondrial metabolism through HIF-1α, as demonstrated in human colon cancer cells." (PMID 33691728, 2021). "In this study, we employed SW480 cells as the prototype of KRAS-driven colon cancer cells and RKO as the prototype of BRAF-driven colon cancer cells." (PMID 34136383, 2021). "Tumors with KRAS codon 13 mutants, in comparison with RAS wild-type colon cancers were more likely to exhibit lower total LN rate (P = 0.05), and the majority of LN were significantly less than 12 (P = 0.05)." (PMID 33784337, 2021). "Studies have reported that BRAF/KRAS induces the activation of the MAPK/ERK signaling pathway, triggering colon cancer." (PMID 35003370, 2021). "Pathway analysis showed that cyclin genes were tightly associated with apoptosis, the cell cycle, hormone ER, the RAS/MAPK pathway, mismatch repair, mTORC1 signaling, KRAS signaling, Akt, and TGFB in colon cancer." (PMID 33996604, 2021). "This synergistic effect can be useful for therapy in colon cancer cells harboring the RAS-mutant and for treating refractory cancers driven by oncogenes, such as KRAS." (PMID 34946546, 2021). "Cost-effectiveness comparison of chemotherapy + anti-EGFR mAb vs. chemotherapy + bevacizumab in (a) KRAS wild-type (b) pan-RAS wild-type and (c) pan-RAS wild-type left-sided colonic tumor." (PMID 34012917, 2021). "Thirdly, we showed by FRET-FLIM imaging an induction of HER2-HER3 dimers after cetuximab treatment in KRAS and BRAF WT colon cancer cells." (PMID 31851321, 2020). "Chromosomal instability is more often observed in left-sided colon cancer than in right-sided, whereas defective genes include adenomatous polyposis coli (APC) and KRAS deletion." (PMID 33045001, 2020). "Since the CMS1–MSI-immune colon cancer subtype is also characterized by high MSI, high levels of BRAF mutations, and low levels KRAS mutations, we decided to explore whether CD68High tumors presented differences in HIF1A expression comparing MSI/MSS, and BRAF and KRAS wild-type versus mutated." (PMID 32231135, 2020). "For colon cancer, the main method to assess the outcome of patients is TNM, pathological grading systems, and some other markers such as KRAS status and BRAF status." (PMID 33304907, 2020). "Expression of oncogenic KRAS (KRASG12V), which is an important driver of colon cancer, improved the survival of detached cells." (PMID 32196494, 2020). "In the YUMC-C1 and YUMC-C2 drug-resistant and metastatic colon cancer cells, respectively, metastatic genes (CDH2, KRAS, CDC42, MCPH1, SRGAP) and markers of stemness (BRACA1 and 2, CD44, KRT5, WNT4, CD29, SAL4) were markedly enhanced." (PMID 33050525, 2020). "For example, KRAS G12D and G12V were reported to occur in 6.9% and 8.2% of colon tumors described in the COSMIC database but were detected in 48.6% and 51.4% of colon tumors analyzed by ACB‐PCR, which has a sensitivity of 10−5." (PMID 31469467, 2020).
colon carcinoma (continued). "In this study, we established OPN stable overexpressing cells using KRAS mutant/wild‐type isogenic pair of colon cancer cell line to investigate the potential role and mechanism of OPN overexpression in colon cancer progression." (PMID 29851214, 2018). "For instance, the KRAS, PTEN and APC genes are well-established tumor drivers in many different tumor types, including colon cancer." (PMID 29621323, 2018). "Here, we wanted to identify RTKs that were potentially activated during treatment with the monoclonal antibody EGFR inhibitor cetuximab in previously identified intermediate cetuximab-sensitive KRAS and BRAF wild-type colon cancer cell lines." (PMID 28032592, 2017). "In vitro studies using wild type KRAS and NRAS colon cancer cells were performed to evaluate the impact of VEGF-A on cetuximab-induced cell death." (PMID 26824184, 2016). "In vitro, VEGF-A induced a resistance toward cetuximab cytotoxicity on three KRAS and NRAS wild type colon cancer cell lines in a VEGFR2 and Stat-3-dependent manner." (PMID 26824184, 2016). "To study a potential role of mutant KRAS/BRAF in Everolimus response, we took the advantage of isogenic colon cancer cell lines with targeted disruption of WT or mutant BRAF alleles, or mutant KRAS knockin or knockout cells." (PMID 27351224, 2016). "In this retrospective study, we evaluated common hot spot gene mutations located downstream of EGFR signaling pathway, the potential prognostic value for KRAS, BRAF, PIK3CA and NRAS was assessed in 228 stage II-III colon cancer." (PMID 27074743, 2016). "In this study, we observed that miR-143 or miR-145 overexpression reduced cell proliferation and migration of mutant KRAS HCT116 colon cancer cells, and sensitized both mutant KRAS (HCT116 and SW480), as well as wild-type KRAS (SW48) cells to cetuximab." (PMID 26824186, 2016). "Alterations of EGFR/MAPK signaling are frequently observed in KRAS and BRAF colon cancer correlating with chemoresistance and poor clinical outcome." (PMID 27323830, 2016). "HGUE-C-1 cells were also treated in culture with cetuximab, an antibody against the extracellular domain of EGFR, since this is a treatment used in advanced colon carcinoma patients and since HGUE-C-1 cells are wild type for KRAS and BRAF." (PMID 25885658, 2015). "The KRAS, ERK and AKT genes have been shown to be critical regulators of colon tumor growth through enhancing survival and reducing apoptosis." (PMID 25889965, 2015). "They will gain recognition in the future as screening test items before drug administration for colon cancer treatment along with BRAF and KRAS." (PMID 25936694, 2015). "The first case is a 72-year-old male patient who presented initially with stage III KRAS wild-type, BRAF wild-type ascending colon cancer in year 2013." (PMID 26472021, 2015). "Recent evidences presented BRAF and KRAS oncogenes are involved in the TGF-β1 pathway which play an important role in induction and maintenance of EMT in colon carcinoma." (PMID 25277203, 2014). "Particularly, in HCT-116 colon carcinoma cells, HIF-1α and HIF-2β regulate the cancer metabolism by overlapping with the KRAS oncogene." (PMID 24804733, 2014). "The top oncogenic signatures identified from male smoking include tumor suppressor genes (PTEN and RB1), colon cancer gene sets (CTIP and SNF5), skin tumor progression protein (ATF2), oncogenic signatures KRAS-600-LUNG and E2F3 pathway genes." (PMID 25621181, 2014). "Currently, only mutant KRAS, mutant BRAF, MSI and the Oncotype DX® Colon Cancer Assay are used in clinical practice." (PMID 24759962, 2013).
colon carcinoma (continued). "Previous reports have shown that both KRAS and β-catenin are able to regulate MYC expression in colon cancer cells." (PMID 23227266, 2012). "While HCT116 harbors mutant KRAS, HT29 colon cancer cells are wildtype for KRAS but harbor mutant BRAF." (PMID 21129190, 2010). "To investigate the dynamic behaviors of KRAS WT, we performed single-molecule observations of transiently expressed tdStayGold-fused molecules localized to the inner leaflet of the PM in living SW48 colon cancer cells." (PMID 40949096, 2025). "A retrospective study showed that KRAS and BRAF mutations had no negative prognostic effect in stage II and III colon cancer." (PMID 40142219, 2025). "Another study found that 83% of KRAS protein was expressed in metastatic colon cancer-diabetic patients compared with 22% in colon cancer-nondiabetic patients." (PMID 40913040, 2025). "Highlighting the complexity of miRNA networks, these findings demonstrate a reciprocal negative regulation between the oncomiR miR-21 and the tumor suppressor miR-145, modulated by KRAS signaling, which collectively governs CSC properties and chemoresistance in colon cancer." (PMID 41476448, 2025). "EFTX-G12V showed strong anti-tumor activity in lung and colon cancer xenograft models without having any off-target effects on wild-type KRAS in physiological tissues such as the kidney, skin, and bladder." (PMID 40805153, 2025). "When adjusted for standard of care (ESCAT I‐II) genes (i.e., PIK3CA, ESR1, and ERBB2 for breast cancer; KRAS, NRAS, and BRAF for colon cancer, etc.), 37 (3.6%), 0 (0%), 1 (0.2%), and 0 (0%) of mutant alleles would have been negative among breast, bowel, lung, and skin cancer samples, respectively." (PMID 40056420, 2025). "This systematic review synthesizes a comprehensive range of studies examining the prognostic significance of NRAS, KRAS, and BRAF mutations within non-metastatic MSI colon cancer." (PMID 38786299, 2024). "Notably, EGFR antibody has been approved as first-line treatment option for KRAS wild-type, EGFR-overexpressing colon cancer patients." (PMID 38961535, 2024). "It has been found that inhibition of BCAM impairs KRAS-mutant colon cancer cells’ specific adhesion to endothelial cells, but not to pericytes, but the mechanism is not known." (PMID 39835116, 2024). "KRAS and NRAS mutations were observed exclusively in non-CDX2-suppressed colon cancers, with no cases in the CDX2-suppressed group bearing such mutations." (PMID 39452477, 2024). "This systematic review aims to investigate how the presence of NRAS, KRAS, or BRAF mutation in non-metastatic MSI colon cancer patients affects outcomes such as DFS, OS, and survival after recurrence (SAR)." (PMID 38786299, 2024). "We reviewed the previous literatures with keywords “colon cancer,” “KRAS,” “NRAS,” and “BRAF,” and there was no agreed conclusion of the driver gene’s role in CRC patients." (PMID 36862900, 2023). "For example, miR-19a inhibits colon cancer angiogenesis by targeting KRAS and VEGFA, and miR-181d reduces cell proliferation, migration, and invasion by triggering PEAK1, a downstream regulator of the EGFR/KRAS pathway." (PMID 36960218, 2023). "Changes in these signaling molecules were observed only in the tissues from the mutant KRAS and SVCT-2-positive human colon cancer cell line SW620 but not in tissues from the mutant KRAS and SVCT-2-negative cell line HCT116." (PMID 36979659, 2023).
colon carcinoma (continued). "In the existing literature and established guidelines, routine testing of KRAS is not recommended in the workup of non-metastatic colon cancer due to a lack of evidence in its utility for determination of adjuvant therapy." (PMID 35323316, 2022). "Indeed, another variation of neoantigen with oncogenic KRAS was identified from RCM1, a commercially available colon cancer cell line." (PMID 35982173, 2022). "In our study, KRAS did not rank high (18 of 23) in importance for guiding prognosis in colon cancer." (PMID 35323316, 2022). "In addition, activated KRAS has been shown to induce HIF1A and ARNT target gene expression in human colon cancer cells." (PMID 34580712, 2022). "In colon cancer, exosomes have been found to transfer mutant oncogenes such as KRAS and SRC to other colon cancer cells lacking these mutations to further promote tumor invasion." (PMID 36139610, 2022). "miR143-3p has been shown to be downregulated in colon cancer samples; upregulation of miR143-3p by transfection of HT-29 colon cancer cell line resulted in decreased expression of ERK5 and its upstream activator, KRAS protein." (PMID 36077521, 2022). "In contrast, NOP56 expression is not a prognostic marker for KRAS-mutant lung, pancreatic and colon cancers." (PMID 35039048, 2022). "This is in keeping with current literature, which has not definitively established KRAS mutation as an independent prognostic factor, especially in stage II and III colon cancer." (PMID 35323316, 2022). "The possibility that iron metabolism might function through KRAS and PI3K-AKT-mTOR signaling pathways in colon cancer provides ideas for future research." (PMID 35118074, 2021). "KRAS, NRAS, BRAF, HER2, and MSI must be evaluated in all patients with advanced colon cancer." (PMID 34541365, 2021). "It was found that expression of NR1H4 is frequently downregulated by DNA methylation and Kirsten rat sarcoma (KRAS) signaling in colon cancer, which implies a negative relationship between NR1H4 and tumor growth." (PMID 34680577, 2021). "It has been reported that in in human KRAS-G12D colon tumor cells, STAT1 can act in a cell-autonomous manner to promote tumor growth, which indicated that inhibition of STAT1 will suppress the KRAS-G12D colon tumor growth." (PMID 34578339, 2021). "The right side colon cancer was observed to have worse CSS than left side colon cancer in KRAS WT patients (HR > 1, p < 0.05) but not in KRAS MT patients (p > 0.05)." (PMID 32547859, 2020). "On the contrary, the five remaining colon cancer cell lines, namely SW48, DIFI, MICOL24, CACO-2 and E705, showed no hyperactivating mutations in KRAS, NRAS, BRAF and PIK3CA genes, with the E705 cell line carrying a silent mutation in PIK3CA gene." (PMID 33233823, 2020). "The researcher concluded that KRAS mutation had no major prognostic value in patients with stage II and III colon cancer and did not influence survival." (PMID 32079384, 2020). "Examining a previously established collection of the normal colonic cells (HCEC) expressing the known oncogenic drivers of colon cancer such as truncated APC and mutant KRAS, we demonstrated that LEF1 was upregulated upon the expression of truncated APC and activated KRAS." (PMID 31623618, 2019). "Therefore, combined targeting of KRAS and MEK nuclear translocation appears to be a promising therapeutic scenario in KRAS mutant colon cancers." (PMID 30833665, 2019). "Mouse models of Kras and Braf mutant tumors showed significant response to vitamin C treatment unlike colon cancer cells wild type for the KRAS pathway, which remained less sensitive to this treatment." (PMID 31288436, 2019). "Therefore, our results demonstrated that NVP-TNKS656 is able to overcome MEK inhibitor resistance in KRAS mutant and PIK3CA mt/β-catenin wt colon cancer cells." (PMID 30944457, 2019).